TNF (tumor necrosis factor)
Diseases named in the same sentence as TNF in open-access papers (continued):
Sharing a sentence is not in itself a finding about the gene and the disease.
ankylosing spondylitis (continued). "This meta-analysis indicated that TNF-α −857 C/T polymorphism might increase the susceptibility of ankylosing spondylitis, especially in Asians." (PMID 27917334, 2016). "Our meta-analysis indicated that the TNF-α −857 C/T polymorphism might increase the risk of ankylosing spondylitis, especially in Asian populations." (PMID 27917334, 2016). "Generating multi-locus genotype frequencies for cases and controls were determined using real data for 3 SNPs (TNF308, TNF863, and TNF1031) in the promoter region of the TNF-alpha locus from cases and controls ascertained for an actual Ankylosing Spondylitis (AS) association study." (PMID 16689984, 2006). "Therefore, the aim of this study was to evaluate whether serum TNC levels are associated with disease activity in ankylosing spondylitis patients treated with conventional cs-DMARDS or anti-TNF agents." (PMID 40564778, 2025). "The analysis shows that IL-17 polymorphisms are associated with clinical parameters in Polish patients with ankylosing spondylitis and have influence on AS severity and potential course of the disease and may be biomarkers of response to anti-TNF drugs in Polish patients." (PMID 34744511, 2021). "The tumor necrosis factor alpha (TNF-α) inhibitor etanercept has been proven to be effective in the treatment of ankylosing spondylitis (AS), while genetic polymorphism may affect drug metabolism or drug receptor, resulting in interindividual variability in drug disposition and efficacy." (PMID 28248857, 2017). "In this report, the authors have presented an anti-TNF-induced neuropathy in an ankylosing spondylitis patient that reversed on drug discontinuation." (PMID 41658656, 2026). "Biosimilar tumor necrosis factor inhibitors provide therapeutically equivalent alternatives to reference biologics for ankylosing spondylitis (AS) management at reduced costs." (PMID 42064804, 2026). "For example, in patients with ankylosing spondylitis, treatment with NSAIDs significantly reduced serum levels of IL-6, IL-17, and TNF-α." (PMID 41010614, 2025). "Most tellingly, lessons from these animal models have supported the development of highly effective therapeutics, expanding our options from the TNF inhibitors that were the only biologic approach approved for ankylosing spondylitis 10 years ago." (PMID 40938333, 2025). "Etanercept, a dimeric fusion protein that inhibits the activity of TNF-α, has shown efficacy in the treatment of ankylosing spondylitis." (PMID 39901933, 2025). "One of the ankylosing spondylitis patients receiving anti-TNF alpha treatment exhibited elevated plasma ANA and dsDNA levels." (PMID 40447321, 2025). "In ankylosing spondylitis (AS), chronic inflammation triggers a cascade of pro-inflammatory cytokines, such as tumor necrosis factor-alpha (TNF-α) and interleukin-17 (IL-17), which drive the expression of MMP-3." (PMID 40277922, 2025). "Further evidence comes from studies in ankylosing spondylitis (AS), which reported reductions in depressive symptoms with TNF-α inhibitors." (PMID 40943274, 2025). "Still, it seems that ankylosing spondylitis patients treated with TNFα inhibitors have lower levels of SUA than patients treated only with non-steroidal anti-inflammatory drugs." (PMID 40136396, 2025). "Patients received anti-TNF-α treatment due to 226 (50.4%) ankylosing spondylitis, 160 (35.7%) RA, 54 (12.1%) psoriatic arthritis, and 8 (1.8%) Behçet's disease." (PMID 39045935, 2024). "Based on our ELISA data, we observed significant increases in multiple pro-inflammatory factors (IL-17, IL-23, TNF-α, IL-1β, and IL-18) in the serum of mice with ankylosing spondylitis (AS) compared to the control group (p < 0.05)." (PMID 39857593, 2024). "The pathogenesis of ankylosing spondylitis, represented by multiple myeloma and lymphoma, is related to tumor necrosis factor-α(TNF-α)." (PMID 38422099, 2024).
ankylosing spondylitis (continued). "TNF is a critical factor in the pathogenesis of ankylosing spondylitis (AS), leading to the development of TNF-targeting therapies for its treatment." (PMID 39649224, 2024). "A phase 3 multicenter, double-blind, randomized controlled trial was conducted in China to compare the efficacy of IBI303, a biosimilar monoclonal antibody against TNFα, with adalimumab in the treatment of ankylosing spondylitis." (PMID 38415452, 2024). "Ankylosing spondylitis was diagnosed, and adalimumab, a tumor necrosis factor (TNF) blocking agent, was initiated." (PMID 38415452, 2024). "A previous study found that MALT1 was positively correlated with Th17 cells, and inflammation and its decrement, along with treatment, reflects the response to TNF inhibitor in ankylosing spondylitis patients." (PMID 38978626, 2024). "For instance, steroids have been associated with changes in the GM, and therapy with the tumor necrosis factor-inhibitor (TNFi), a biologic DMARD, was correlated with restoration of the perturbed GM in ankylosing spondylitis." (PMID 38715051, 2024). "In a landmark study, the authors demonstrated for the first time that tumor necrosis factor alpha (TNFα) is heavily expressed in inflamed sacroiliac joints of patients with ankylosing spondylitis (AS,), now named axial spondyloarthritis (axSpA)." (PMID 38864856, 2024). "Tumor necrosis factor (TNF) plays a pivotal role in the inflammatory cascades characteristic of ankylosing spondylitis (AS), particularly in activating immune cells and perpetuating chronic inflammation in the spinal column and sacroiliac joints." (PMID 39493161, 2024). "Tumour necrosis factor-alpha (TNF-α) inhibitors are commonly used in the treatment of ankylosing spondylitis (AS) due to their effectiveness in reducing inflammation and slowing disease progression." (PMID 39493161, 2024). "Comparing the efficacy of adalimumab and biosimilar agents is crucial in addressing the limitations faced by patients with ankylosing spondylitis (AS) who require treatment with TNF-α inhibitors." (PMID 38415452, 2024). "Of the patients receiving anti-TNF-α therapy, RA was noted in 30 (43.5%), ankylosing spondylitis in 29 (42%), psoriatic arthritis in 7 (10.1%), and Behçet's disease in 3 (4.3%)." (PMID 39045935, 2024). "For instance, a study using an anti-TNF antibody in a mouse model demonstrated improved fracture healing, while contradictory results were observed in an ankylosing spondylitis patient cohort treated with a TNF-α inhibitor." (PMID 38051594, 2023). "Cost and drug toxicity frequently deter the long-term use of anti-tumor necrosis factor (TNF) agents in ankylosing spondylitis (AS)." (PMID 36960229, 2023). "One (1.8%) patient was treated initially with steroids and tocilizumab and was followed up with the diagnosis of ankylosing spondylitis, and was already on tumor necrosis factor alpha antagonist." (PMID 36945962, 2023). "Circulating Th17 are increased in patients with ankylosing spondylitis (AS), a prototype of axSpA, but this can be effectively attenuated with tumor necrosis factor (TNF) inhibitors." (PMID 37143677, 2023). "The aim of our study was to assess the impact of treatment with tumor necrosis factor-alpha (TNFα)-inhibitors on tryptophan metabolism in patients with ankylosing spondylitis (AS)." (PMID 37646896, 2023). "This is consistent with another study that reported lower pGSN in men compared to women in a cohort of ankylosing spondylitis patients undergoing anti-TNF-alpha therapy and controls." (PMID 36899335, 2023). "HLA-B*27 is associated with a more chronic and extensive disease course in male children and adolescents with enthesitis-related arthritis (ERA) and with a better response to anti-TNF treatment in ankylosing spondylitis." (PMID 37277844, 2023). "Another paper documented five patients with LE following anti-TNF-α treatment for ankylosing spondylitis." (PMID 37175894, 2023).
ankylosing spondylitis (continued). "Surprisingly, there was no significant changes in serum levels of tryptophan and its metabolites in patients with ankylosing spondylitis treated with TNFα inhibitors, despite clinical improvement." (PMID 37646896, 2023). "Disease activity was reduced with TNF-α inhibitors in all AS patients, as seen in Bath Ankylosing Spondylitis Disease Activity Index (BASDAI) scores shifting from high to moderate disease activity." (PMID 37180165, 2023). "The aim of our study was to assess the impact of biologic treatment with TNFα-inhibitors on tryptophan metabolism in patients with ankylosing spondylitis." (PMID 37646896, 2023). "Large-scale and long-term follow-up clinical trials are still necessary to further investigate the safety of tumor necrosis factor alpha inhibitors in ankylosing spondylitis treatment." (PMID 36865909, 2023). "This cohort study develops and validates models of the probability of short-term response to tumor necrosis factor inhibitor treatment in individual patients with active ankylosing spondylitis." (PMID 35289857, 2022). "Is it possible to predict short-term treatment response to tumor necrosis factor inhibitors (TNFis) accurately in patients with active ankylosing spondylitis (AS)?" (PMID 35289857, 2022). "Multiple clinical trials found that infliximab, an anti-TNF-α biologics, was effective for ankylosing spondylitis (AS) and RA." (PMID 35887724, 2022). "Circulating miR-145 has recently been described as a marker of therapeutic response to anti-TNF in patients with ankylosing spondylitis." (PMID 35955723, 2022). "Over the past decade, tumor necrosis factor-α inhibitors (TNFi) have become the cornerstone for the treatment of ankylosing spondylitis (AS)." (PMID 34575390, 2021). "This study aimed to investigate drug retention rates for various TNF inhibitors (TNFis) commonly prescribed to Korean patients with ankylosing spondylitis (AS) in the Korean College of Rheumatology Biologics registry (KOBIO; December 2012–June 2016)." (PMID 34211991, 2021). "This study evaluated the possibility of clinical remission suggested by the treat-to-target strategy and identified predictors of clinical remission in 139 patients with ankylosing spondylitis (AS) receiving tumor necrosis factor-α inhibitors (TNFi)." (PMID 34575390, 2021). "In this study, we assessed the effects of one-year anti-TNF therapy on ACE and ACE2 production in RA and ankylosing spondylitis (AS) in association with other biomarkers." (PMID 35155468, 2021). "Studies into ankylosing spondylitis (AS) and its relationship with immune imbalance are controversial, and the correlation between the efficacy of TNF-α inhibitor and changes in immune imbalance is unclear." (PMID 32560733, 2020). "Reductions of cardiovascular events due to treatment with TNF-α inhibitors were also observed in ankylosing spondylitis and psoriatic arthritis." (PMID 33053859, 2020). "For example, active serum MMP3 levels decreased in both ankylosing spondylitis (AS) and RA after anti-TNFα treatment." (PMID 32782251, 2020). "We aim to generate an artificial neural network (ANN) model to predict early TNF inhibitor users in patients with ankylosing spondylitis." (PMID 33219239, 2020). "Golimumab (Janssen Biotech Inc., Horsham, PA, USA) is a fully human anti-tumor necrosis factor alpha (TNFα) monoclonal antibody shown to be effective in patients with RA, ankylosing spondylitis, and PsA." (PMID 32143685, 2020). "Demographic characteristics of patients with ankylosing spondylitis (n = 167) and patients initiating anti-TNF treatment (n = 68)." (PMID 32083089, 2020). "Golimumab is a selective immunosuppressive and anti-inflammatory TNF-α-inhibitor applied subcutaneously to treat rheumatoid and psoriatic arthritis, as well as ankylosing spondylitis." (PMID 32421085, 2020). "Previous work summarizing the effectiveness of anti-TNF therapy in RA and ankylosing spondylitis (AS) has suggested a a positive spin-off for the periodontium." (PMID 33193432, 2020).
ankylosing spondylitis (continued). "Recent SLRs and NMAs have compared efficacy within a class of therapies (i.e., TNF inhibitors) and across all then-available biologics for the treatment of ankylosing spondylitis." (PMID 32107666, 2020). "Differential effects of different TNFα inhibitors on T cell function were only reported in ankylosing spondylitis." (PMID 31105703, 2019). "The purpose of this study was to investigate possible effects of anti-TNF alpha therapy on cardiorespiratory fitness and physical functional capacity of patients with ankylosing spondylitis (AS)." (PMID 30761840, 2019). "Rudwaleit and colleagues reported the first systematic analysis of the parameters correlated with clinical responses to anti-TNF therapy in active ankylosing spondylitis patients in 2004." (PMID 30941119, 2019). "The patient has been receiving adalimumab and methotrexate for the last 3 years due to ankylosing spondylitis and was seropositive to varicella zoster virus prior to the introduction of TNF-α antagonists." (PMID 30732563, 2019). "Therapeutic targeting of tumour necrosis factor (TNF)-α is highly effective in ankylosing spondylitis (AS) patients." (PMID 30157966, 2018). "The patient had been diagnosed with ankylosing spondylitis 20 years ago and had been receiving treatment with NSAIDs and anti TNFα drugs." (PMID 32185305, 2018). "Relatively weak effects showing the prognostic value of pGSN in ankylosing spondylitis patients undergoing anti-TNF-α monoclonal antibody-infliximab therapy were also noted." (PMID 30149613, 2018). "Men with TNF-α-related ankylosing spondylitis reported significant improvement in erectile function after three months of TNF-α blocker therapy." (PMID 28763467, 2017). "Our patient was diagnosed with ankylosing spondylitis since years and was treated with adalimumab, a tumour necrosis factor-alpha (TNF-α) inhibitor." (PMID 28056818, 2017). "Currently, along with traditional disease modifying anti-rheumatic drugs (DMARDs), TNF-α, IL-12/23 and IL-17 are available for treatment of such diseases as ankylosing spondylitis (AS) and psoriatic arthritis (PsA)." (PMID 29283375, 2017). "One such example is ankylosing spondylitis (AS), which is a chronic inflammatory arthritis, where there is simultaneous destruction and formation of bone and where TNFα has a role in the pathogenesis." (PMID 28974711, 2017). "In regards to ankylosing spondylitis, 79.0% of the subjects in anti-TNF (+/-DMARD) group and 41.1% of the subjects in the DMARD group persisted with their treatments." (PMID 27556964, 2016). "Biological agents such as tumor necrosis factor alpha (TNFα) inhibitor have been used in clinical research to treat ankylosing spondylitis (AS), showing efficacy against disease reactiveness and positive effects on joint function." (PMID 26832154, 2016). "In another study of ankylosing spondylitis, 61% of patients chose injectable anti-TNF because of convenience." (PMID 27007811, 2016). "Many studies indicated that the TNF-α gene plays a vital role in the pathogenesis of ankylosing spondylitis because of the location and relevant biological properties of the gene site." (PMID 27917334, 2016). "On the other hand, endothelial function of ankylosing spondylitis patients was impaired compared with healthy controls, and improved after tumor necrosis factor-alpha blockade." (PMID 27383120, 2016). "We performed a meta-analysis to evaluate the effect of anti–tumor necrosis factor (TNF) therapy on the frequency of extra–articular manifestations (EAMs) in patients with ankylosing spondylitis (AS)." (PMID 25888248, 2015). "The advent of anti-tumor necrosis factor-α (TNFα) drugs has changed the course of ankylosing spondylitis (AS)." (PMID 26205000, 2015). "The patient was on tumor necrosis factor alpha antagonist (TNFA) (Etanercept) for severe Ankylosing spondylitis." (PMID 26075132, 2015).
ankylosing spondylitis (continued). "A 42-year-old man with a long history of Ankylosing spondylitis presented with acute urinary retention three months after he was started on a TNF alpha antagonist." (PMID 26075132, 2015). "Sequential treatment of ankylosing spondylitis (AS) that includes tumour necrosis factor-α antagonists (anti-TNF agents) has been applied in most of the Western countries." (PMID 26451133, 2015). "TNF-α also plays a central role in the pathogenesis of psoriasis, psoriatic arthritis and ankylosing spondylitis." (PMID 24896264, 2014). "Infliximab (TNF-alpha inhibitor, IV) improves not only ankylosing spondylitis, but also the vitiligo, probably due to anti-TNF-alpha activity blockage." (PMID 24665368, 2014). "In keeping with these results, an independent correlation of OPG levels with asymmetric dimethylarginine (ADMA), another biomarker of endothelial cell activation, has been disclosed in ankylosing spondylitis patients undergoing anti-TNF-α therapy." (PMID 25184828, 2014). "This is illustrated in a synthesis of eight placebo-controlled trials of TNF-α inhibitors in ankylosing spondylitis, each reporting treatment effects on between two and five of a total six test instruments." (PMID 24636388, 2014). "HLA-B27 positivity in patients with ankylosing spondylitis predicts a poorer prognosis and a better response to anti-TNFα treatment." (PMID 24490631, 2014). "The anti-TNF therapy downregulated the frequency of Th17 cells in these mice, corroborating previous findings in ankylosing spondylitis patients; therefore, downmodulation of IL-17 is a conserved effect of TNF blocking." (PMID 25140115, 2014). "Data from clinical studies on the long-term efficacy and safety of anti-tumor necrosis factor (TNF)-α therapy in patients with ankylosing spondylitis (AS) are scarce." (PMID 23786760, 2013). "The data of 12 healthy and 12 ankylosing spondylitis subjects (treated with anti-TNF-α stabilized), with a mean age of 51.42 and 49.42 years; mean BMI of 23.08 and 25.44 kg/m2 were collected." (PMID 22931459, 2012). "The ASAS criteria evolved from the idea that the earlier the recognition of patients with ankylosing spondylitis, the better the efficacy of tumor necrosis factor blockers." (PMID 22650358, 2012). "While adalimumab is licensed for ankylosing spondylitis (AS), open uncontrolled studies suggest therapeutic efficacy of TNF-inhibitors in juvenile onset AS (JoAS)." (PMID 23095307, 2012). "Of 150 of patients on anti-TNF (82 RA, 34 ankylosing spondylitis, 32 psoriatic arthritis, and 4 for other indications), 20 (13.3%) cases were reported weight gain in first year while on anti-TNF (18 females and two males)." (PMID 22927859, 2012). "In a study of 106 patients with ankylosing spondylitis (AS), a significant increase in weight was observed after 12 months of treatment with anti-TNF therapy (2.2 ± 3.9 kg), which remained elevated at 24 months." (PMID 22927859, 2012). "Identifying ankylosing spondylitis (AS) patients who are likely to benefit from tumor necrosis factor-alpha (TNF-α) blocking therapy is important, especially in view of the costs and potential side effects of these agents." (PMID 21689401, 2011). "AS outpatients who started TNF-α blocking therapy were included in the Groningen Leeuwarden Ankylosing Spondylitis (GLAS) study, an ongoing prospective longitudinal observational cohort study with follow-up visits according to a fixed protocol." (PMID 21689401, 2011). "The study has also shown that improvements in the QOL of patients treated with anti-TNF therapies reported in PsA are much higher than those reported in RA and slightly higher than those reported in ankylosing spondylitis (AS)." (PMID 20391480, 2010). "At week 12 of adalimumab treatment, Bath Ankylosing Spondylitis Disease Activity Index 50 responses were achieved by 40.8% of 326 patients with AS who had received prior anti-TNF therapy and by 63.0% of 924 patients with AS who were naive to TNF antagonist." (PMID 20553600, 2010).